TWIST1 (twist family bHLH transcription factor 1)
Diseases named in the same sentence as TWIST1 in open-access papers (continued):
Sharing a sentence is not in itself a finding about the gene and the disease.
glomerular disease (1 paper, 2021). "During glomerular disease, Twist1 in podocytes limited CCL2-induced recruitment of monocytes/macrophages into the glomerulus and thereby mitigated damage driven by TNF-α–elaborating proinflammatory macrophages." (PMID 34369383, 2021). "Because the podocyte is a primary target of injury during glomerular disease and exhibits features of both epithelial and immune cell lineages, we explored the impact of Twist1 in podocytes on glomerular damage after immune-mediated or toxic insult." (PMID 34369383, 2021). "Through this crosstalk, Twist1 in podocytes ameliorated podocytopathy and restrained glomerular disease progression." (PMID 34369383, 2021). "Podocytes are specialized epithelia that exhibit features of immune cells and could therefore mediate unique effects of Twist1 on glomerular disease." (PMID 34369383, 2021). "As TLR4 is expressed on podocytes and is upregulated in glomerular disease, we isolated and cultured primary podocytes from WT and Twist1-PKO animals and then stimulated TLR4 on the podocytes with LPS for 6 hours to mimic the podocyte activation that occurs during inflammatory injury." (PMID 34369383, 2021). "Our current studies demonstrate that Twist1-regulated CCL2 generation played a pivotal role in crosstalk between podocytes and macrophages during the development of podocyte injury and glomerulopathy." (PMID 34369383, 2021).
glomerulosclerosis (1 paper, 2021). A hardening of the kidney glomerulus caused by scarring of the blood vessels. "Immunofluorescence staining for the macrophage marker CD64+ in the glomeruli showed augmented numbers of glomerular macrophages in the Twist1-PKO mice compared with WT, which could have contributed to the exaggerated podocyte injury and glomerulosclerosis in the Twist1-PKO animals." (PMID 34369383, 2021).
Granuloma (1 paper, 2013). A compact, organized collection of mature mononuclear phagocytes, which may be but is not necessarily accompanied by accessory features such as necrosis. "Application of the MWCNT granuloma model will be a useful tool to explore the potential interactions of Twist1 with the transcription factors, NF-κB and PPARγ in subsequent studies of pulmonary granulomatous disease." (PMID 24322444, 2013). "Based on this observation we hypothesized that Twist1 mRNA and protein expression might become elevated in alveolar macrophages from animals bearing granulomas induced by carbon nanotube instillation." (PMID 24322444, 2013).
idiopathic pulmonary arterial hypertension (1 paper, 2020). A sporadic form of pulmonary arterial hypertension (PAH) characterized by elevated pulmonary arterial resistance leading to right heart failure. "The levels of Twist1 and PDGFB are higher in PAE cells isolated from idiopathic pulmonary arterial hypertension (IPAH) patients compared to those from healthy controls." (PMID 32371931, 2020).
intestinal cancer (1 paper, 2022). "We successfully established ZEB2 and TWIST1 knockdown intestinal cancer stable transitional cell lines by sgRNA and shRNA." (PMID 35884488, 2022).
intracranial meningioma (1 paper, 2021). A meningioma that arises within the cranial cavity. "Our protein analyses of E-cadherin, N-cadherin, SNAIL, SLUG, and TWIST1 and two forms of β-catenin demonstrated a close association between the Wnt signaling pathway activation and epithelial-mesenchymal transition in intracranial meningiomas." (PMID 33915799, 2021). "Our investigation on EMT transcriptional factors TWIST1, SNAIL, and SLUG demonstrated their strong expression, where SNAIL and SLUG were associated to higher grades and they represent a good indicator of the progression of intracranial meningiomas." (PMID 33915799, 2021). "It is possible that, in addition to genetic changes, transcription factors SNAIL, SLUG, and TWIST1, which repress E-cadherin synthesis by binding to its promoter, further contribute to the reduction in E-cadherin expression levels in intracranial meningioma samples." (PMID 33915799, 2021).
lentivirus infection (1 paper, 2020). Virus diseases caused by the Lentivirus genus. "Twist1 was overexpressed or knocked down in DPCs following different adenovirus or lentivirus infection." (PMID 32974352, 2020).
lipid metabolism disorder (1 paper, 2024). "Compared with the Control group, the mRNA expression of Srebf2, Scap, Hmgcr, Soat1, Npc1, Snai3, Twist1, Itgav, Vegfc, and Tgfbr1 has higher expression in model group, indicating that there is lipid metabolism disorder in model mice." (PMID 38724499, 2024).
liver tumor (1 paper, 2022). "However, the role that TWIST1 gene plays in the process of liver tumor metastasis in vivo is still not well understood." (PMID 35052775, 2022).
lung squamous cell carcinoma (1 paper, 2025). "In a study titled “Vasculogenic mimicry and expression of Twist1 and KAI1 correlate with metastasis and prognosis in lung squamous cell carcinoma” 157 cases of lung squamous cell carcinoma were investigated to determine the impact of VM on OS." (PMID 40786517, 2025).
mastocytosis (1 paper, 2023). A clonal myeloproliferative neoplasm characterized by the proliferation and accumulation of neoplastic mast cells in one or multiple organs or organ systems. "Further studies on the relevance of oncogenes FOXQ1, TWIST1, and ERG as second-hit mutations in mastocytosis and novel therapeutic targets are needed." (PMID 37762215, 2023). "Importantly, three oncogenes—FOXQ1, TWIST1, and ERG—were identified as differentially methylated in mastocytosis patients, for the first time." (PMID 37762215, 2023).
mitral valve disease (1 paper, 2015). "Here, we examine VIC phenotypes in established mouse models of mitral valve disease using SMA, Periostin, Twist1 and Vimentin expression." (PMID 26527432, 2015).
Myocardial fibrosis (1 paper, 2025). "Twist1 expression levels reflect HF-related myocardial fibrosis and therapeutic response." (PMID 40283937, 2025). "However, how Twist1 plays a role in HF ventricular remodeling characterized by myocardial fibrosis has not been clarified." (PMID 40283937, 2025).
Nephroblastoma (1 paper, 2022). An embryonal neoplasm characterized by the presence of epithelial, mesenchymal, and blastema components. "Transgenic-adipo-PGC-1α mice displayed reduced adipocyte hypertrophy, associated with a reduction in molecules within the TGF-β signaling pathway, and of the inflammatory markers nephroblastoma-overexpressed/cellular communication network factor 3 (NOV/CCN3), Twist1, and IL-6." (PMID 35740043, 2022).
nephrolithiasis (1 paper, 2018). The presence of a calculus in the pelvis of the kidney; this is most often composed of mineral salts and proteins. "Consistent with our study, Liu and co‐workers demonstrated that Twist was not expressed in normal kidneys, whereas activated Twist1 was highly expressed in the tubular epithelial cells from nephrolithiasis patients." (PMID 29314610, 2018).
neutropenia (1 paper, 2015). A decrease in the number of neutrophils found in the blood. "The high PB blast counts and LDH levels suggest the aggressiveness of Twist1-associated AML, whereas the thrombocytopenia and neutropenia probably represent a poorer marrow reserve in Twist1-overexpressing AML patients." (PMID 26832848, 2015).
nonalcoholic steatohepatitis (1 paper, 2021). "The present study focuses on the role of TWIST1, TWIST2 and PPARγ in nonalcoholic steatohepatitis progression." (PMID 33879188, 2021).
osteoporosis (1 paper, 2025). A condition of reduced bone mass, with decreased cortical thickness and a decrease in the number and size of the trabeculae of cancellous bone (but normal chemical composition), resulting in increased fracture incidence. "Ganoderic acid A might play an important role in the prevention of osteoporosis by modulating the PIK3CA/p‐Akt/TWIST1 signaling pathway." (PMID 40236832, 2025). "Therefore, it is reasonable to speculate that Ganoderic acid A can promote bone formation in osteoblasts by activating PIK3CA to catalyze the PI3K/Akt signaling pathway and then inhibiting the protein expression of TWIST1, thus playing a positive role in preventing and treating osteoporosis." (PMID 40236832, 2025).
ovarian endometrioid carcinoma (1 paper, 2025). "We found a correlation between FAM64A and TWIST1 in high-grade serous OC, yet not in ovarian endometrioid carcinoma, which may be closely related to the small sample size." (PMID 40424038, 2025).
ovarian endometriosis (1 paper, 2015). A non-neoplastic disorder characterized by the growth of endometrial tissue in the ovaries. "A study including patients with ovarian endometriosis analyzed mRNA expression of the stemness-related gene OCT4 and TWIST1." (PMID 26198055, 2015).
parathyroid disease (1 paper, 2025). "Although classified as VUS, several candidate genes previously reported to be associated with parathyroid disease, including ITPR2, IL21R, MMP14, TWIST1 and ESR2 were identified in three patients with cancer-type tumors." (PMID 40434298, 2025).
pulmonary edema (1 paper, 2013). Accumulation of fluid in the lung tissues causing disturbance of the gas exchange that may lead to respiratory failure. "To determine whether Twist1-Tie2 signaling mediates lung vascular permeability in sepsis-induced lung injury in vivo, we exposed whole lung of living adult mice to the endotoxin, lipopolysaccharide (LPS), which induces the development of pulmonary edema and ARDS in humans with sepsis." (PMID 24023872, 2013).
retinal degeneration (1 paper, 2019). Degeneration of the retina. "Evaluation of regions associated with overt retinal degeneration and RPE phenotypic changes showed decreased detection of the mitochondrial marker COX-IV after PGC-1 deletion, whereas the EMT markers—collagen-VI, vimentin, TWIST1, and ZEB1- were increased." (PMID 31101737, 2019).
rheumatoid arthritis (1 paper, 2015). A chronic, systemic autoimmune disorder characterized by inflammation in the synovial membranes and articular surfaces. "In vitro assays have confirmed that expression of POSTN and TWIST1 are elevated in fibroblast-like synoviocytes (FLSs) of rheumatoid arthritis patients (RA-FLSs) and are crucial for the migration and invasion of FLSs stimulated with interleukin (IL)-1β." (PMID 25981515, 2015).
Robinow syndrome (1 paper, 2024). Robinow syndrome (RS) is a rare genetic syndrome characterized by limb shortening and abnormalities of the head, face and external genitalia. "Similarly, we show that in the chicken cranial mesenchyme, Robinow syndrome-associated hFZD2 variants cause an ectopic increase in nuclear β-catenin and TWIST1 expression, alongside a decrease in cartilage matrix protein levels." (PMID 38967226, 2024).
Salmonella Infections (1 paper, 2024). Infections with bacteria of the genus SALMONELLA. "GO analysis indicated proteins' involvement in some specific functions, such as adherens junction, tight junction, RNA transport, protein processing in the endoplasmic reticulum, proteoglycans in cancer, Salmonella infection, and cell cycle, especially, IMP2 and Twist1." (PMID 38506089, 2024).
scleroderma (1 paper, 2018). Scleroderma is a rare autoimmune connective tissue disorder characterized by abnormal hardening of the skin and, sometimes, other organs. "Geniposide, which has a protective effect on endothelial cells in the bleomycin‐induced scleroderma mouse model, remarkably decreased Twist1 expression." (PMID 29314610, 2018). "The expression of Twist1, an important EndMT factor, was increased in bleomycin‐induced scleroderma mouse models and cultured human umbilical vein endothelial cells." (PMID 29314610, 2018).
Sepsis (1 paper, 2013). Sepsis is defined as life-threatening organ dysfunction caused by a dysregulated host response to infection. "The Twist1-Tie2 pathway might therefore represent a new target for therapeutic strategies for sepsis-induced ARDS." (PMID 24023872, 2013).
serous ovarian cancer (1 paper, 2024). "In high-grade serous ovarian cancer, the overexpression of the CD73 molecule with EMT markers (e.g., Snail, vimentin, or Twist1) was associated with poor prognosis of survival." (PMID 38791431, 2024).
spindle cell carcinoma (1 paper, 2022). "Silencing TNFR1 in SCC cells inhibits cell proliferation, reduces UBCH10, Twist1, Sox2, and c-Myc levels, converts spindle cell carcinomas into well-differentiated SCCs, dampened tumor burden, and blocked metastasis." (PMID 36270982, 2022). "When injected via tail vein, KALLU+ lung SCC cells that highly expressed TNFR1/TNF, Sox2, c-Myc, Twist1, Bcl2, and UBCH10, generated dedifferentiated spindle cell carcinomas with epithelial–mesenchymal transition markers in mouse lungs." (PMID 36270982, 2022). "In contrast, silencing TNFR1 reduced levels of stemness, Twist1 (an epithelial–mesenchymal transition–EMT), and oncogenic UBCH10, an E2 ubiquitin-conjugating enzyme, converted dedifferentiated spindle cell carcinoma to well-differentiated SCC, and inhibited metastasizing SCCs." (PMID 36270982, 2022).
steatosis (1 paper, 2021). Increased lipid within the cytoplasm of cells. "The present study will continue previous work to explore the role and possible mechanism of TWIST1, TWIST2, and PPARγ in the development of hepatocyte steatosis." (PMID 33879188, 2021).
transient ischemic attack (1 paper, 2020). A brief attack (from a few minutes to an hour) of cerebral dysfunction of vascular origin, with no persistent neurological deficit. "Interestingly, TWIST1 expression was higher in lesions categorized as asymptomatic based on absence of signs of a transient ischemic attack prior to endarterectomy (fold change = -0.754, p = 0.0275, n = 127)." (PMID 31917787, 2020).
Truncus arteriosus (1 paper, 2013). A single arterial trunk arises from the cardiac mass. "In addition to the formation of ectopic OFT sympathetic-like neurons, Twist1;Wnt1-Cre CKOs also display completely penetrant persistent truncus arteriosus (PTA)." (PMID 23555309, 2013).
Uterine leiomyoma (1 paper, 2022). The presence of a leiomyoma of the uterus. "The expression of all those genes, except TWIST1, was higher in tumor-adjacent tissues than in tissues neighboring uterine leiomyoma in cancer-free patients." (PMID 36140779, 2022).
tumor (909 papers, 2005 to 2026). "Equally, Hsp90 inhibition has been linked to the downregulation of STAT3 and TWIST1 transcription pathways, thereby inhibiting tumor progression, metastasis, and chemoresistance in diverse tumors." (PMID 39936995, 2025). "TWIST1 gene expression has been found to be upregulated in multiple types of cancers, closely associated with tumor invasiveness, metastasis, and poor prognosis." (PMID 39905312, 2025). "Correlation analyses indicate that GREM1 is significantly positively correlated with genes associated with tumor invasion and metastasis, including TWIST1 and PDGFRA." (PMID 40066442, 2025). "Elevated TWIST1 expression in primary tumours is frequently linked to a poor prognosis and increased metastatic potential." (PMID 40869272, 2025). "The assembly of the Bcl-2/Twist1 complex facilitated the nuclear transport of Twist1 and triggered the transcription of genes linked to enhanced tumor cell plasticity, metastasis, and vasculogenic mimicry." (PMID 40556662, 2025). "Twist1 is a transcription factor associated with palate development and oral jaw size in model organisms and tumor metastasis." (PMID 38979003, 2024). "Apart from the physiological and biological roles in embryonic development and organogenesis, Twist1 has been associated with tumorigenesis, tumor progression, metastasis, stemness, and vasculogenic mimicry." (PMID 37784111, 2023). "Increased expression of TWIST1 is directly associated with tumour invasion and metastasis and mediates the loss of E-cadherin and increases the expression of mesenchymal markers fibronectin, N-cadherin, and vimentin." (PMID 36766756, 2023). "Several genes and pathways known to be associated with aggressive tumor biology were found to be overexpressed among high Twist1 cases." (PMID 36900319, 2023). "Many of the observed genes and pathways associated with high Twist1 expression are known to be involved in immunoregulation, lymphocyte differentiation, and aggressive tumor biology." (PMID 36900319, 2023). "Similar to our observations in in vitro-cultured cells, analysis of lysates from mouse-derived tumors indicated that overexpression of TWIST1 alleviated the decreases in the expression of stemness markers caused by USP51 knockdown in the tumor cells." (PMID 37422632, 2023). "While the simulation of AKT2 overexpression reached attractors supporting tumor development by inhibiting apoptosis and activation of epithelial to mesenchymal transition (EMT), in silico knockout of TWIST1 prevents tumor-associated characteristics." (PMID 35465155, 2022). "A high level of expression of the TWIST1-tumor-stroma signature was associated with a poor OS and EFS of NB patients in both the SEQC and the Kocak datasets." (PMID 35022561, 2022). "Twist1, a member of the basic helix–loop–helix family of transcription factors, has multiple functions that are associated with fibrotic diseases and tumor progression." (PMID 35182235, 2022). "TWIST1 protein is expressed in several tumours and is associated with tumour invasion and chemotherapy resistance." (PMID 35802537, 2022). "TWIST1 is a basic helix-loop-helix (bHLH) transcription factor that is essential during embryonic development and is associated with tumor metastasis and growth." (PMID 35408897, 2022). "While a great number of studies has implicated that Twist1 is overexpressed in various carcinomas and plays a vital role in tumor initiation, stemness, angiogenesis, dissemination and chemoresistance." (PMID 35219305, 2022). "For example, Twist1, a key transcription factor associated with tumor cell-associated EMT, promotes increased expression of thymidine phosphorylase (TP), a rate-limiting PPP enzyme belonging to the thymidine catabolic pathway." (PMID 36059624, 2022).